BCHE (butyrylcholinesterase)
Diseases named in the same sentence as BCHE in open-access papers (continued):
Sharing a sentence is not in itself a finding about the gene and the disease.
Hyperglycemia (6 papers, 2011 to 2024). An increased concentration of glucose in the blood. "At 200 μg/mL, the fractions inhibited acetylcholinesterase and butyrylcholinesterase as well as α-amylase and α-glucosidase, indicating that they can slow neurodegeneration and hyperglycemia." (PMID 38140461, 2023). "This can be attributed to the fact that chronic hyperglycemia influences inflammatory mediator which inhibit the activity of serum BChE." (PMID 28376867, 2017). "Moreover, by hydrolyzing ghrelin, BChE could lessen its retinal protective effects, like inhibiting hyperglycemia-induced cell death, reducing the production of reactive oxygen species, and protecting retinal function and structure." (PMID 37138337, 2023).
Insulin resistance (6 papers, 2006 to 2025). Increased resistance towards insulin, that is, diminished effectiveness of insulin in reducing blood glucose levels. "It is likely that the link between BChE and insulin resistance underlies the associations we observed between higher BChE levels and worse glucose metabolism." (PMID 40243328, 2025). "Further investigations are needed to clarify the mechanistic contribution and potential diagnostic value of elevated BChE activity in hepatic steatosis, insulin resistance and related metabolic diseases." (PMID 40243328, 2025). "However, there is evidence showing that serum butyrylcholinesterase is associated with adiposity, serum lipid profile and insulin resistance in humans." (PMID 19680557, 2009). "Higher plasma BChE activity is linked to liver fat accumulation, as well as impaired glucose tolerance and insulin resistance, independent of liver fat." (PMID 40243328, 2025). "Moreover, our findings support earlier studies conducted on German women and Japanese adults, which identified a link between BChE levels and insulin resistance." (PMID 40724174, 2025). "An interesting finding from our study is that BChE activity is related to both liver fat content and insulin resistance, but these associations appear to be independent of each other." (PMID 40243328, 2025). "A high level of BCHE is responsible for the development of insulin resistance." (PMID 30678306, 2019). "Butyrylcholinesterase may be indirectly involved in the pathogenesis of insulin resistance." (PMID 17096857, 2006). "The enzyme butyrylcholinesterase (EC 3.1.1.1.8) does not have a well-defined physiological function, although it may modulate the phenotypic expression of dyslipidemia and insulin resistance." (PMID 17096857, 2006).
liver dysfunction (6 papers, 2012 to 2022). "The statistical analysis showed that BChE fall < 2000 U/L was associated with the onset of posttransplant liver dysfunction and SOS (p < 0.05)." (PMID 31185690, 2019). "BChE is determined during routine laboratory examination as an indicator for liver dysfunction, since progressive liver damage is associated with compromised serum BChE activity." (PMID 25933219, 2015). "Considering all liver dysfunctions, only SOS had a strong association with BChE percentage drop (p < 0.005)." (PMID 31185690, 2019). "Our explanation is that apparently there is no need for an additional analysis of BCHE deficiency in WD patients with low serum levels of BCHE, since liver dysfunction as an essential aspect of WD offers an obvious reason for this." (PMID 36291607, 2022). "There have been many studies on plasma butyrylcholinesterase in liver dysfunction." (PMID 23028565, 2012). "We investigated whether all patients with reduced BChE activity suffered from liver dysfunction." (PMID 25762852, 2015). "Firstly, since BChE is synthesized in liver, this assay is unsuitable for patients with major liver dysfunction and the authors currently possess no data for a reliable interpretation of the BChE activity in these patients." (PMID 31320703, 2019).
multiple sclerosis (6 papers, 2015 to 2025). A progressive autoimmune disorder affecting the central nervous system resulting in demyelination. "Multiple Sclerosis (MS) - BChE plays a significant role in multiple sclerosis (MS) through deacylation of proteolipid protein (PLP) a main component of myelin." (PMID 40612057, 2025). "Furthermore, BChE appears to play an important role in the development of multiple sclerosis." (PMID 36902286, 2023).
pancreatic cancer (6 papers, 2020 to 2025). "Reduced BChE activity in blood plasma is associated with a shorter survival time in pancreatic cancer (PC) patients." (PMID 40282999, 2025). "Lower BChE plasma levels were also successfully associated with worse cancer-specific prognosis, in a cohort of pancreatic cancer patients." (PMID 39229253, 2024). "In this 2020 study, the authors managed to associate the BChE plasma levels independently with pancreatic carcinoma survival rates in a single—institution study." (PMID 39229253, 2024). "As these conditions have been previously linked with pancreatic cancer (PC), the purpose of the present study was to evaluate the prognostic impact of plasma BChE in PC." (PMID 32375339, 2020).
amyloid (5 papers, 2010 to 2026). "The observed increase in [11C]4 uptake in the white matter-rich areas, such as cerebellum, is expected if one considers that the increased demand for BChE is provoked by amyloid-associated damage." (PMID 33995675, 2021). "It has also been reported that AChE and BChE co-localize within the brain in amyloid plaques to form insoluble β-amyloid fibrils." (PMID 20550720, 2010). "Neurofibrillary tangles and amyloid plaques express AChE and BChE activity in AD." (PMID 20550720, 2010).
Hepatic steatosis (5 papers, 2009 to 2025). Steatosis is a term used to denote lipid accumulation within hepatocytes. "Further investigations are needed to clarify the mechanistic contribution and potential diagnostic value of elevated BChE in hepatic steatosis and metabolic diseases." (PMID 40243328, 2025). "In BChE-deficient mice treated with a high-fat diet, increased serum total cholesterol and hepatic TAG levels were associated with hepatic steatosis." (PMID 40698664, 2025). "The gene identified as the best predictor of hepatic steatosis by the regression analysis, butyrylcholinesterase (BCHE) has been mostly studied in the context of its effect on the brain's cholinergic system." (PMID 19680557, 2009). "Thus, high BChE levels could prompt further testing for fatty liver in this population." (PMID 40243328, 2025). "This suggests that BChE could not just be a marker for liver steatosis, but may indicate processes in hepatocytes that contribute to impaired glucose metabolism." (PMID 40243328, 2025).
memory impairment (5 papers, 2020 to 2025). "The reduction in serum BChE activity reflects metal‐induced neurotoxicity and association with memory impairment in animals and humans." (PMID 36514774, 2022). "Low BChE expression is accompanied with higher stress-induced aggression and ghrelin levels in stress models, and BChE knockout mice exhibit cognitive and memory impairments." (PMID 33061920, 2020). "Moreover, based on the phytochemical, behavioural, and biochemical results, we hypothesize that F. ammoniacum could possibly act directly as a free radical scavenger or regulator to inhibit cholinesterases (AChE and BChE), oxidative stress, and memory impairments induced by scopolamine." (PMID 33669503, 2021).
cocaine addiction (4 papers, 2013 to 2018). "Gene transfer of a human cocaine hydrolase (hCocH) derived from butyrylcholinesterase (BChE) by 5 mutations (A199S/F227A/S287G/A328W/Y332G) has shown promise in animal studies for treatment of cocaine addiction." (PMID 23840704, 2013). "Further studies are needed in order to confirm this preliminary result and clarify the role of BCHE and its variants in cocaine dependence." (PMID 24312228, 2013). "This feature encouraged exploration of treatments for cocaine addiction and overdose, by raising BChE blood levels and enhancing its efficiency by modifying key residues in and around the enzyme’s catalytic site." (PMID 29535625, 2018). "BChE has also been tested as a novel therapeutic agent for cocaine dependence: a quadruple mutant hydrolase derived from human BChE suppressed cocaine toxicity and abolished drug-primed reinstatement in rats." (PMID 24312228, 2013). "Butyrylcholinesterase (BChE; EC 3.1.1.8) and its genetically engineered variants are being developed as therapeutic enzyme “bioscavengers” of organophosphorus acid anhydrides (OPAA) to prevent or treat OPAA poisoning and also have been investigated to reverse cocaine addiction." (PMID 25077141, 2014).
epilepsy (4 papers, 2022 to 2025). A brain disorder characterized by episodes of abnormally increased neuronal discharge resulting in transient episodes of sensory or motor neurological dysfunction, or psychic dysfunction. "For instance, rare or low-frequency variants causing rare diseases such as hearing impairment, corneal dystrophy, Stargardt disease, epilepsy, biotinidase, and butyrylcholinesterase deficiencies were identified in South Asian populations (GIH, ITU, PJL, and STU)." (PMID 40136566, 2025).
Hypoalbuminemia (4 papers, 2014 to 2020). The concentration of albumin in the blood circulation is below the lower limit of normal. "Furthermore, low BChE activity was associated with histologically confirmed nerve plexus invasion at the time of curative resection as well with anemia, poor performance status, cachexia, hypoalbuminemia, hypocholesterinemia and ascites, all signs of exceedingly advanced disease." (PMID 32375339, 2020). "On univariate analysis, performance status; anemia; hypoalbuminemia; preoperative levels of BChE, corrected calcium, and C-reactive protein; and distant metastasis status were significantly associated with OS." (PMID 24741368, 2014). "As the production of BChE and albumin in the liver occur in a coupled fashion, mechanisms leading to a decrease of serum BChE levels might be comparable to those leading to hypoalbuminemia." (PMID 30737542, 2019). "Indeed, a positive correlation between serum albumin and BChE activity was observed, despite the fact that 8 patients (20%) with severe hypoalbuminemia (plasma albumin < 20 g/L) received albumin substitution (rs = 0.53, Spearman's rank correlation test)." (PMID 25762852, 2015).
ischemic stroke (4 papers, 2019 to 2023). A stroke disorder caused by obstruction of blood flow to the brain, due to thrombotic (local blood clot formation) or embolic (due to a blood clot or other material traveling from another site) event. "Also, our results indicated an increase in plasma cholinesterase (BCHE) in the severe group, which is upregulated in patients suffering from mild ischemic stroke." (PMID 33995121, 2021).
sarcopenia (4 papers, 2019 to 2025). Progressive decline in muscle mass due to aging which results in decreased functional capacity of muscles. "Recently, it has been reported that butyrylcholinesterase is related to muscle mass and strength and is a new biomarker to identify elderly people at risk for sarcopenia." (PMID 35587474, 2022).
anemia (3 papers, 2014 to 2024). A reduction in the number of red blood cells, the amount of hemoglobin, and/or the volume of packed red blood cells. "Despite the small size of this derivation cohort, this study identified elevated HbA1c as the strongest risk factor for the development of POD, followed by a decrease in BChE activity, postoperative anemia, and age, respectively." (PMID 39713214, 2024). "In summary, this study identified an elevated HbA1c as the strongest risk factor for the development of POD followed by the decrease in BChE activity and postoperative anemia, respectively age." (PMID 39713214, 2024).
bladder cancer (3 papers, 2019 to 2022). "DARS together with BCHE were among 344 downregulated genes in tissue samples investigated for bladder cancer pointing to a common interrelation of both genes." (PMID 33378362, 2020).
coronary artery disease (3 papers, 2017 to 2025). "Coronary Artery Disease (CAD) - Evaluating BChE activity in serum provides valuable perspective into disease severity and prognosis in coronary artery disease (CAD), especially acute coronary syndrome (ACS)." (PMID 40612057, 2025).
endothelial dysfunction (3 papers, 2011 to 2024). In vascular diseases, endothelial dysfunction is a systemic pathological state of the endothelium (the inner lining of blood vessels) and can be broadly defined as an imbalance between vasodilating and vasoconstricting substances produced by (or acting on) the endothelium. "In this age group (6–9 years), we found a significant association both between ALT and BChE with markers of inflammation, endothelial dysfunction, and IR, in turn resulting in a positive correlation between liver enzymes and leptin concentration." (PMID 33665176, 2021). "The present study also demonstrated the vasculo-protective effects of the BChE, which alleviated the endothelial dysfunction in isolated murine aortas stimulated by Ang2, LPS or high GLUC." (PMID 39769283, 2024).
glioblastoma (3 papers, 2022 to 2025). The most malignant astrocytic tumor (WHO grade IV). "High levels of cholinesterase BCHE were also detected, a characteristic shared with glioblastomas and neuroblastomas (OMIM 177400)." (PMID 39022728, 2024).
Lewy body dementia (3 papers, 2023 to 2025). A progressive form of dementia characterized by the presence of protein deposits called Lewy bodies in the midbrain and cerebral cortex, and loss of cholinergic and dopaminergic neurons. "BChE expression is increased in the brains of AD and Lewy bodies dementia patients, when AChE expression is markedly decreased." (PMID 38887858, 2024). "For dementia with Lewy bodies (DLB), biomarkers may include the RNA expression levels in small EVs circulating in plasma or altered protein levels in plasma EVs, such as gelsolin and butyrylcholinesterase." (PMID 37685965, 2023).
liver cancer (3 papers, 2018 to 2025). An epithelial or non-epithelial malignant neoplasm that arises from the liver. "First, we characterized six different liver cancer cell lines in terms of their acetylcholinesterase/butyrylcholinesterase (ACHE/BCHE) expression and activity." (PMID 29371671, 2018). "Next, we studied AChE/BChE enzymatic activity in our panel of liver cancer cell lines using a modified Ellman method based assay." (PMID 29371671, 2018). "However, more comprehensive and up-to-date studies are needed to determine the exact role of BChE in liver cancer and its place in clinical practice." (PMID 40142216, 2025). "In liver cancer, it is thought that BChE levels may be a prognostic indicator." (PMID 40142216, 2025).
protein-energy malnutrition (3 papers, 2014 to 2018). A nutritional deficit that is caused by inadequate protein or calorie intake. "Similarly, low BChE levels have been reported during stress and inflammation, as well as in cases of protein-energy malnutrition and other clinical conditions." (PMID 24741368, 2014).
Pseudocholinesterase deficiency (3 papers, 2020 to 2025). "Pseudocholinesterase deficiency is a rare disorder of the enzyme butyrylcholinesterase that can lead to delayed emergence following exposure to depolarizing neuromuscular blocking agents." (PMID 41510418, 2025). "Congenital butyrylcholinesterase deficiency (BCHED) is a rare autosomal recessive genetic disorder caused by a pathogenic mutation in the BCHE gene." (PMID 39465744, 2024). "We aimed to identify the genetic basis of disease in a patient presenting with butyrylcholinesterase deficiency in order to confirm the diagnosis, expand BCHE gene mutation spectrum, and elucidate potential genotype-phenotype associations to inform management." (PMID 39465744, 2024). "Pseudocholinesterase deficiency is caused by butyrylcholinesterase (BCHE) gene mutation, a gene that provides instructions for making the pseudocholinesterase enzyme." (PMID 33150117, 2020).
schizophrenia (3 papers, 2020 to 2025). A major psychotic disorder characterized by abnormalities in the perception or expression of reality. "BChE has also been implicated in schizophrenia, where increased expression of BChE was observed in ketamine dosed rats, a known model of schizophrenia, and following chronic exposure to cigarette smoke during pregnancy." (PMID 35719055, 2022). "Furthermore, BChE has found to be upregulated in schizophrenia patients, and when treated with rivastigmine, an inhibitor of BChE and acetylcholinesterase, their quality of life was improved." (PMID 35719055, 2022). "In addition, these findings further support the hypothesis that the beneficial effects of propranolol in conditions such as PTSD, agitation, and schizophrenia may not be solely due to its β-adrenergic blockade, but also to its BChE inhibitory activity." (PMID 41322300, 2025).
viral infection (3 papers, 2017 to 2024). "BChE knock-out mice exhibit slightly increased serum AG levels while re-introduction of BChE via viral infection can decrease the serum AG level." (PMID 33647468, 2021). "While a link between AChE activity and HIV-1 viral load has not been made, infection with herpes simplex virus type 1 (HSV-1) results in a steady decline in the enzymatic activity of AChE12, indicating that AChE or BChE may play a role in viral infection." (PMID 28338013, 2017).
Abdominal obesity (2 papers, 2021 to 2025). Excessive fat around the stomach and abdomen. "Indeed, an increase in plasma levels of BChE has been reported in individuals with abdominal obesity and MetS." (PMID 33665176, 2021). "Animal experiments have shown that mice lacking BChE or BChE knockout (−/−) developed central obesity and exhibited an impaired lipid profile." (PMID 40724174, 2025).
Anorexia (2 papers, 2014 to 2017). Lack of desire to eat (loss of appetite). "Decreased levels of BChE have been described in anorexia, as well as in critically ill patients or frail elderly." (PMID 29113384, 2017). "One of the possible mechanisms for such BChE activity decrease in cancer patients could be secondary anorexia accompanying malignancy." (PMID 24741368, 2014).
Apnea (2 papers, 2013 to 2021). Lack of breathing with no movement of the respiratory muscles and no exchange of air in the lungs. "Our results provide, in two small animal models, the proof of principle that SC-induced apnea can be reversed by administration of plant-produced recombinant human BChE." (PMID 23536865, 2013). "Treatment of SC-induced apnea offers an alternative use for recombinant BChE, beyond scavenging of organophosphate nerve agents in a chemical warfare/terrorism scenario, that may provide increased patient safety in the use of RSI in both hospital and pre-hospital care." (PMID 23536865, 2013).
brain tumors (2 papers, 2021 to 2025). "This suggests a potential link between BChE activity levels and the rate of cell growth in brain tumors, further supporting the notion of a biphasic role for BChE in tumor progression." (PMID 40678419, 2025). "In less aggressive brain tumors, BChE activity was low to moderate, whereas in aggressive tumors, it was high." (PMID 40678419, 2025). "Increased AChE and BChE activity was also observed in brain tumors, including GBM." (PMID 34959693, 2021).
cocaine use disorder (2 papers, 2018 to 2020). A substance-related disorder that involves the recurring use of cocaine despite negative consequences. "An engineered variant of human butyryl cholinesterase (Alb-BChE; TV-1380), with increased catalytic activity and a longer serum elimination half-life than the wild-type, is also being developed as a potential therapeutic agent for cocaine use disorder." (PMID 30041697, 2018).